TREM2 (triggering receptor expressed on myeloid cells 2)
Diseases named in the same sentence as TREM2 in open-access papers (continued):
Sharing a sentence is not in itself a finding about the gene and the disease.
Alzheimer disease (continued). "The loss of TREM2 renders macrophages less phagocytic, and the authors propose that this renders the individual more prone to Alzheimer’s disease." (PMID 30013551, 2018). "Rare heterozygous coding variants in the triggering receptor expressed in myeloid cells 2 (TREM2) gene, conferring increased risk of developing late-onset Alzheimer's disease, have been identified." (PMID 29906661, 2018). "Rare coding variants in the triggering receptor expressed on myeloid cells 2 (TREM2) are associated with increased risk for Alzheimer's disease (AD), but how they confer this risk remains uncertain." (PMID 30341064, 2018). "Rare partial loss-of-function mutations in the TREM2 gene are associated with an increase in the risk of Alzheimer’s disease dementia, comparable to that associated with the APOE ɛ4 allele." (PMID 30239611, 2018). "The TREM2 R62H variant, found in one of our patients, is associated with increased late onset Alzheimer’s disease (AD) risk, whilst only the TREM2 R47H variant is associated with early onset AD." (PMID 29450646, 2018). "Genetic variants of the Triggering Receptor Expressed on Myeloid Cells-2 (TREM2) confer increased risk of developing late-onset Alzheimer’s Disease (LOAD) and other neurodegenerative disorders." (PMID 29037207, 2017). "The present study provides evidence that TREM2 is required for preventing loss of memory and learning in Alzheimer’s disease by regulating C/EBPα-dependent CD36 expression and the consequent Aβ phagocytosis." (PMID 28894284, 2017). "The inheritance of a mutant variant of the TREM2 gene, R47H, confers a markedly increased risk for developing late-onset and early-onset Alzheimer’s disease (AD)." (PMID 28320424, 2017). "Of particular note, in late 2012, two independent groups identified coding alterations in the Triggering Receptor Expressed on Myeloid Cells-2 (TREM2) gene that dramatically increased the risk of developing late-onset Alzheimer’s Disease (LOAD)." (PMID 29037207, 2017). "From our study, the H157Y mutation at the sheddase site likely increases risk of Alzheimer's disease by accelerating proteolytic loss of TREM2 from the cell surface." (PMID 28855301, 2017). "A functional TREM2 single nucleotide polymorphism is important in the etiology of Alzheimer's disease (AD) and frontotemporal dementia, and TREM2 mRNA is increased in monocytes in AD." (PMID 28588439, 2017). "TREM2 plays a critical role in the alleviation of Alzheimer’s disease by promoting Aβ phagocytosis by microglia, but the detailed molecular mechanism underlying TREM2-induced direct phagocytic activity of Aβ remains to be revealed." (PMID 28894284, 2017). "Loss-of-function (LOF) mutations in TREM2, which have been linked to risk of Alzheimer’s disease, and ALS, reduce phagocytosis of aggregated protein by microglia." (PMID 28302159, 2017). "Crucially, we also show that the Alzheimer's disease‐associated H157Y TREM2 variant was shed more rapidly than wild type from HEK293 cells, possibly by a novel, batimastat‐ and ADAM10‐siRNA‐independent, sheddase activity." (PMID 28855301, 2017). "Genetic mutations in triggering receptor expressed on myeloid cells 2 (TREM2) have been linked to a variety of neurodegenerative diseases including Alzheimer’s disease, amyotrophic lateral sclerosis, frontotemporal dementia and Parkinson’s disease." (PMID 29611543, 2017). "TREM2 variants have been identified as risk factors for Alzheimer’s disease (AD) and other neurodegenerative diseases (NDDs)." (PMID 28768545, 2017). "A subset of heterozygous TREM2 variants such as R47H, R62H and H157Y are associated with increased risk of Alzheimer's disease (AD)." (PMID 28855301, 2017). "Heterozygous missense mutations in the triggering receptor expressed on myeloid cells 2 (TREM2) have been reported to significantly increase the risk of developing Alzheimer’s disease (AD)." (PMID 28197095, 2017).
Alzheimer disease (continued). "The authors of a recent study of an extended family with Alzheimer’s disease report multiple segregating risk factors of high impact including ApoE4 and TREM2, where the effects of the variants were interpreted as additive." (PMID 27120335, 2016). "The R47H coding variant of the triggering receptor expressed on myeloid cells-2 (TREM2) increases the risk of Alzheimer's disease (AD) similar to apolipoprotein E4." (PMID 28149270, 2016). "Individuals with rare mutations in the gene that encodes a protein called TREM2 have a substantial risk of developing Alzheimer’s disease in their mid-60s." (PMID 27995897, 2016). "Recent studies, however, have implicated that TREM2 variant is also a risk factor of Alzheimer disease, frontotemporal dementia, Parkinson disease, and more recently, ALS, due to impaired cell surface transport of the protein." (PMID 26943047, 2016). "In contrast, mutations associated with Alzheimer’s disease make it harder for TREM2 to bind to molecules known as glycosaminoglycans." (PMID 27995897, 2016). "Although TREM2 mutation is reported to be related to Nasu-Hakola disease and Alzheimer's disease, little is known about the association between TREM2 and gliomas." (PMID 26506595, 2016). "Genetic analyses showed that the triggering receptor expressed in myeloid cells 2 (TREM2) p.R47H variant increases the risk for Alzheimer’s disease (AD)." (PMID 27887626, 2016). "Recent genome-wide association studies revealed TREM2 rs75932628-T variant to be associated with Alzheimer’s disease (AD) and other neurodegenerative diseases." (PMID 27051467, 2016). "Lately, genome-wide association studies (GWAS) revealed TREM2 gene variant rs75932628-T to be associated with Alzheimer’s disease (AD) and other neurodegenerative diseases, such as Parkinson’s disease, frontotemporal dementia and amyotrophic lateral sclerosis." (PMID 27051467, 2016). "Mutations in TREM2 are associated with several diseases, including Nasu-Hakola disease, frontotemporal dementia, and Alzheimer’s disease (AD)." (PMID 26792193, 2016). "TREM2 is also known to be associated with Alzheimer’s disease (AD) and other neurodegenerative diseases." (PMID 26332043, 2015). "For example, TREM2 is a predisposing factor for late-onset Alzheimer's disease and was also present in the microglia module in all 3 data sets in the present study." (PMID 26002684, 2015). "TREM2 encodes for triggering receptor expressed on myeloid cells 2 and has rare, coding variants that associate with risk for late-onset Alzheimer’s disease (LOAD) in Caucasians of European and North-American origin." (PMID 25886450, 2015). "In particular, mutations in TREM2 increase the risk for Alzheimer’s disease and other neurodegenerative disorders." (PMID 26337043, 2015). "Association between TREM2 and Alzheimer’s disease (AD) was initially reported by two independent groups, who identified a rare heterozygous missense mutation in TREM2, p.R47H (rs75932628-T), that increased AD risk by about 2–4.5 fold." (PMID 25886450, 2015). "They concluded that Trem2 rare heterozygous variants were linked with a significantly elevated risk of Alzheimer’s disease." (PMID 24663666, 2014). "We believe that a reduced function of TREM2 is key to the pathogenic effect of the risk variants associated with Alzheimer’s disease." (PMID 25113539, 2014). "TREM2 is another gene known to be involved in inflammatory responses and the association found with Alzheimer’s disease corroborates the involvement of immunological pathways in this disease." (PMID 25113539, 2014). "For example, rare variants in TREM2 were recently found to be associated with increased risk of Alzheimer’s disease by using whole-genome and whole-exome sequencing (WES)." (PMID 24948216, 2014). "Complete sequencing was performed on 281 individuals with Alzheimer’s disease and 504 controls, and the analysis of the TREM2 gene showed excessive TREM2 mutations in those with the disease compared to control subjects." (PMID 24663666, 2014).
Alzheimer disease (continued). "The characterization of one of these TREM2 mutations in very large sample of patients with Alzheimer’s disease has allowed researchers to measure precisely the importance of this association between TREM2 mutations and disease." (PMID 24663666, 2014). "Recent genome-wide association studies linked variants in TREM2 to a strong increase in the odds of developing Alzheimer’s disease." (PMID 24893973, 2014). "This study was the first to report that the Trem2 gene is associated with a triply increased risk of Alzheimer’s disease." (PMID 24663666, 2014). "Recent studies have identified a rare coding variant (p.R47H) in TREM2 that confers a high risk for Alzheimer's disease (AD)." (PMID 24439484, 2014). "Recently the R47H variant of TREM2 was reported to be associated with Late-onset Alzheimer's disease (LOAD)." (PMID 23662159, 2013). "Our results suggest that the TREM2 p.R47H substitution is a risk factor for frontotemporal dementia and Parkinson’s disease in addition to Alzheimer’s disease." (PMID 23800361, 2013). "With this in mind we set out to assess the genetic association of the Alzheimer’s disease-related risk variant in TREM2 (rs75932628, p.R47H) with other related neurodegenerative disorders." (PMID 23800361, 2013). "It is interesting to note that a heterozygous variant (p.R47H) in TREM2 has recently been shown to increase the risk for Alzheimer's disease." (PMID 23870839, 2013). "A rare variant in the Triggering Receptor Expressed on Myeloid cells 2 (TREM2) gene has been reported to be a genetic risk factor for Alzheimer’s disease by two independent groups (Odds ratio between 2.9-4.5)." (PMID 23800361, 2013). "Such distinct expression signatures raise the possibility that TREM2 variants may play a role in modulating inflammatory signaling relevant to cardio-metabolic and Alzheimer's disease." (PMID 41683566, 2026). "Interestingly, both Siglec-3 and TREM-2 have been associated with increasing the risk of Alzheimer’s disease, but in an opposite way." (PMID 40948752, 2025). "Some other TREM2 variants contribute to the risk of Alzheimer’s disease (AD) and frontotemporal dementia, while deleterious TYROBP variants are globally extremely rare and their role in neurodegenerative diseases remains unclear." (PMID 40301889, 2025). "Prior studies have revealed that in Alzheimer’s disease, TREM2-deficient microglia present impaired activation of the mTOR signaling pathway, resulting in decreased ATP levels and obstructed biosynthetic pathways that in turn, trigger an abnormal increase in microglial autophagy." (PMID 40242752, 2025). "Trem2 haploinsufficiency has been linked to an increased risk for Alzheimer's disease and microglial dysfunction, while complete TREM2 loss causes Nasu‐Hakola disease, an autosomal recessive genetic disorder that affects both the central nervous system and the skeleton." (PMID 40716081, 2025). "Furthermore, a decline in DNA methylation within intron 1 of the TREM2 gene in peripheral white blood cells of Alzheimer’s disease (AD) patients has been linked to elevated TREM2 mRNA expression, indicating its potential as a biomarker for AD." (PMID 40244232, 2025). "Since the majority of TREM2 variants linked to Alzheimer’s disease (AD) are suggested to result in disease mechanisms through loss-of-function mechanisms, enhancing TREM2 expression—even in patients without any TREM2 mutations—has been proposed as an alternative therapeutic approach." (PMID 40806186, 2025). "SinceK186 is known to be critical for TREM2–DAP12 interaction andW191 has been potentially linked to Alzheimer’s disease, thissuggests that W191 may play a key role in mediating the interactionbetween TREM2 isoform-219 and DAP12." (PMID 41298271, 2025).
Alzheimer disease (continued). "TREM2 has been implicated in Alzheimer's disease and other neurodegenerative disorders." (PMID 39113887, 2024). "The soluble variant of TREM2 (sTREM2) has emerged as a valuable biomarker for AD pathology and cognitive degeneration, as sTREM2 levels in cerebrospinal fluid (CSF) increase during the early symptomatic phase of Alzheimer’s disease." (PMID 39596378, 2024). "Understanding the exact pathophysiological mechanisms underlying the involvement of triggering receptor expressed on myeloid cells 2 (TREM2) related microglia activation is crucial for the development of clinical trials targeting microglia activation at different stages of Alzheimer’s disease (AD)." (PMID 38961148, 2024). "Variants of Trem2 have been shown to be strongly associated with Alzheimer's Disease (AD) risk." (PMID 38825965, 2024). "The potential importance of TREM2 in neuronal health was first indicated by large-scale genetic studies that identified rare TREM2 point variants, namely R47H and R62H, as risk factors for developing late-onset Alzheimer’s disease (AD)." (PMID 39315272, 2024). "Rare variants associated with Alzheimer’s disease (AD) in the Triggering Receptor on Myeloid Cells 2 (TREM2) gene, along with common variants in the membrane-spanning 4-domains subfamily A (MS4A) gene cluster, have implicated the innate immune system in AD pathogenesis." (PMID 38760857, 2024). "As an example, the loss of DNA methylation in three CpG loci in the intron 1 of the triggering receptor expressed on myeloid cells 2 gene (TREM2, an Alzheimer’s disease susceptibility gene) results in a higher expression of TREM2 in leucocytes of Alzheimer’s patients." (PMID 36978899, 2023). "Subsequent studies have found that TREM2 mutations may increase the susceptibility to the development of various neurodegenerative diseases such as Alzheimer's disease (AD)." (PMID 37013543, 2023). "TREM2 p.R47H may therefore act to increase the risk of Alzheimer’s disease via a partial loss of a protective function of microglia." (PMID 37990275, 2023). "Furthermore, TREM2-related microglial activation measured by sTREM2 seems to have different natures and associations with Alzheimer's disease biomarkers in each stage of the disease." (PMID 37942087, 2023). "Finally in M_SC4, increased expression of Ncf1/p47phox has been reported in phagocytic microglia and upregulation of Tyrobp and Trem2 (a M_SC4 top marker gene) are known markers for DAMs, Alzheimer’s disease-associated microglia with phagocytic activity." (PMID 37293629, 2023). "Similarly, variants in the TREM2 (R47H, H157Y, and L211P) genes, which are closely associated with Alzheimer’s disease in the Caucasian population, were not replicated in Japanese descendants." (PMID 36873109, 2023). "Coding alterations in TREM2, a transmembrane glycoprotein expressed on myeloid lineage cells that modulates innate immune function, dramatically increase the risk of developing late-onset Alzheimer’s disease (LOAD)." (PMID 37371067, 2023). "Although previous studies reported increased CSF soluble TREM2 (sTREM2) in different clinical stages of Alzheimer’s disease, the exact association between Alzheimer’s disease hallmarks such as amyloid-beta and tau pathology remains unclear." (PMID 37942087, 2023). "However, in the hippocampus of patients with Alzheimer’s disease, the higher levels of DNA methylation were reported to be due to the enrichment of 5-hydroxymethycytosine associated with upregulation of TREM2 expression." (PMID 37107654, 2023). "The rs75932628 (p.R47H) TREM2 variant is a well-established risk factor for Alzheimer’s disease." (PMID 37990275, 2023).
Alzheimer disease (continued). "Changes in microglial response may underlie the increased Alzheimer’s disease risk in TREM2 p.R47H carriers." (PMID 37990275, 2023). "Moreover, we identified an important role for TREM2, of which several genetic variants are a well-known risk factor for Alzheimer’s disease and other neurodegenerative diseases, in individuals who deviate from their chronological age." (PMID 36911498, 2023). "Since TREM2 loss-of-function mutations and HSV1 serological status are both linked to Alzheimer’s disease, this work poses the question whether genetic or virus-induced alterations of TREM2 activity predispose to post-infection neurological pathologies." (PMID 37595041, 2023). "Loss-of-function variants of TREM2 are associated with increased risk of Alzheimer’s disease (AD), suggesting that activation of this innate immune receptor may be a useful therapeutic strategy." (PMID 36635496, 2023). "TREM2 encoding the transmembrane receptor protein TREM2 is a risk gene of Alzheimer’s disease (AD), and the impairment of TREM2 functions in microglia due to mutations in TREM2 may significantly increase the risk of AD by promoting AD pathologies." (PMID 37044212, 2023). "Indeed, TREM2-deficient microglia show decreased expression of glycolytic genes and impairment of cell energetic and biosynthetic metabolism in Alzheimer’s disease." (PMID 35359989, 2022). "Moreover, TREM2 can promote the states of microglia to disease associated microglia (DAMs), which can restrict plaque growth in an Alzheimer’s disease model." (PMID 36463233, 2022). "The R47H variant of TREM2 shows a rare mutation within the ligand-binding region of the receptor, which abrogates the response to PS and other putative ligands and increases the risk of neurodegenerative pathologies as Alzheimer disease." (PMID 35723745, 2022). "Mutation in TREM2 gene is a strong risk factor of Alzheimer’s disease." (PMID 35663580, 2022). "Loss-of-function variants of TREM2 are associated with increased risk of Alzheimer’s disease (AD)." (PMID 35191835, 2022). "Recent studies have identified TREM2 as a risk factor for Alzheimer’s disease (AD)." (PMID 35658903, 2022). "Missense mutations (e.g., R47H) of TREM2 increase risk of Alzheimer's disease (AD)." (PMID 33823153, 2021). "The TREM2*R47H mutation triples the carrier’s likelihood of Alzheimer’s disease." (PMID 34707490, 2021). "TREM2 is a microglial receptor genetically linked to the risk for Alzheimer’s disease (AD)." (PMID 34893068, 2021). "Interestingly, two of the common TREM2 variants observed in Alzheimer’s disease can bind to amyloid-β similarly to TREM2 but fail to trigger amyloid-β internalization and exhibit reduced signaling responses." (PMID 34838047, 2021). "APOE and Trem2 are major genetic risk factors for Alzheimer’s disease (AD), but how they affect microglia response to Aβ remains unclear." (PMID 34099706, 2021). "Importantly, dysfunctional microglia, such as that caused by TREM2 mutations also promote Alzheimer’s disease pathogenesis." (PMID 32780728, 2020). "On other hand, in Trem2-deficient Alzheimer disease (AD) mice, status of neurofibrillary tangles remains uncertain; it may either increase or decrease." (PMID 32973484, 2020). "Genetic variations of TREM2 have been implicated as a risk factor of Alzheimer’s disease (AD)." (PMID 33093587, 2020). "Here, we used human iPSC‐derived microglia (iPS‐Mg) generated from donors harboring specific TREM2 mutations previously characterized as hypomorphic variants in Alzheimer’s disease and Nasu Hakola disease (NHD), and identified deficits in microglial metabolic regulation and associated functions." (PMID 31907987, 2020). "Thus, TREM2 genetic variants, which interfere with this binding, increase the risk of Alzheimer’s disease." (PMID 32892753, 2020).